FAP (fibroblast activation protein alpha)
Diseases named in the same sentence as FAP in open-access papers (continued):
Sharing a sentence is not in itself a finding about the gene and the disease.
colorectal cancer (continued). "Another single-cell and spatial analysis revealed interaction of FAP + fibroblasts and SPP1 + macrophages in colorectal cancer, and their presence is negatively correlated with lymphocyte infiltration and predicted a poor patient survival." (PMID 36585688, 2022). "FAP and HGF have an important role in increasing vascularization in patients with colorectal cancer, and their expression levels are significant for predicting liver and LN metastases." (PMID 35330327, 2022). "The tetravalent bispecific mAb RG7386 (RO874813, a FAP mAb coupled with death receptor 5 (DR5) agonist), which binds FAP+ fibroblasts and DR5+ tumour cells, induced tumour regression in a colorectal cancer mouse model." (PMID 35158891, 2022). "In colorectal cancer (CRC), tumor-specific FAP+ fibroblasts and SPP1+ macrophages colocalized in the tumor area, which were proved contributed to desmoplastic TME." (PMID 36313703, 2022). "A further study investigated the potential of FAP imaging compared with FDG imaging in 35 patients with gastric, duodenal and colorectal cancer." (PMID 34638433, 2021). "Recently, circulating fibroblast activation protein α (FAPα) shows good specificity for colorectal cancer (CRC) diagnosis, and the combination of FAPα and other multiple markers all show high sensitivity for early detection of CRC." (PMID 28415791, 2017). "TAVO423 is a FAP × LRRC15 × HYAL trispecific AbEn that effectively degraded HA, delayed tumor growth, and enhanced the efficacy of various therapeutics in an in vivo HA-rich colorectal cancer model." (PMID 41228205, 2025). "Similarly, in colorectal cancer (CRC) where FAP was detected in the cancer cells and surrounding stromal cells containing fibroblasts, an elevated expression of FAP were identified to be aiding in the development of CRC." (PMID 39579201, 2024). "It has been suggested that the interactions between FAP+ CAFs and SPP1+ macrophages could promote the formation of a desmoplastic TME in colorectal cancer." (PMID 38115703, 2023). "FAP+ fibroblasts and SPP1+ macrophages were mostly enriched in tumor tissue, and a high correlation between the infiltration of MSCs and myeloid cells was found in patients across 14 colorectal cancer datasets." (PMID 35365629, 2022). "High expression of FAP has been proved to be related to a poor prognosis in pancreatic ductal adenocarcinoma, colorectal cancer and gastric cancer, but none of their patients underwent NCT." (PMID 36387219, 2022). "In colon cancer fibrosis, a positive correlation was reported between tumor–specific FAP+ fibroblasts and SPP+ macrophages in the colorectal cancer-containing cohort, and immunofluorescence staining and spatial transcriptomics verified their close localization." (PMID 36569953, 2022). "FAP+ fibroblasts and SPP1+ macrophages are the major components of TME in colorectal cancer, which are characterized as major contributors to the desmoplastic tumor structure and immunotherapy resistance against PD-L1 in colorectal cancer." (PMID 35898884, 2022). "In a mouse model of transplantable colorectal carcinoma (CRC), it was found that fibroblasts expressing high levels of FAPα recruited myeloid cells via CCL2, which resulted in resistance to anti-PD-1 immune checkpoint therapy that was eliminated by targeting the FAPα." (PMID 36555218, 2022). "In keeping with these observations, a radiolabelled anti‐FAP antibody (sibrotuzumab) showed highly selective uptake by tumors but not normal tissues in patients with colorectal carcinoma or non‐small‐cell lung cancer." (PMID 33082953, 2020). "Preliminary clinical trials have substantially demonstrated no efficacy of anti-FAP strategy, both by direct targeting using the monoclonal antibody sibrotuzumab in lung and colorectal cancer, and by inhibiting the enzymatic function of FAP using talabostat." (PMID 30871158, 2019).
colorectal cancer (continued). "In MM mouse models, depletion of FAPα+ macrophages significantly boosted the efficacy of anti-PD-1/PD-L1 antibody therapy but not anti-CTLA-4 therapy; this combinatorial strategy also exerted enhanced anti-tumor effects in EL4 lymphoma and CT26 colorectal carcinoma models." (PMID 41614659, 2026). "Similarly, next-generation IL-15-armored, FAP-targeting CAR-iNKT therapy MiNK-215, designed to target the tumor stroma, further enhanced endogenous anti-tumor activity in human organoid models of treatment-resistant colorectal cancer liver metastases." (PMID 40718496, 2025). "Notably, preclinical studies have shown that fibroblasts orchestrating TLS formation in malignant tumors such as melanoma or colorectal cancer are exclusively FAP negative." (PMID 39909044, 2025). "Interestingly, FAP+CAF‐secreted CCL2 has previously been shown to activate myeloid‐derived suppressor cells (MDSC), resulting in tumour growth and proliferative suppression of T cells in colorectal cancer." (PMID 39743376, 2025). "However, no FAP-targeted therapy has demonstrated efficacy in colorectal cancer patients, as both sibrotuzumab (a FAP-targeted mAb) and talabostat (a small molecule FAP-inhibitor) were incapable of successfully passing phase II trials." (PMID 36418422, 2022). "However, another study concerning colorectal cancer did not obtain statistical significance regarding FAP expression." (PMID 25775399, 2015). "Moreover, prior studies addressing FAP expression presented no coherent conclusion based on single-patient cohort evaluations, even with similar tumor types, such as colorectal cancer." (PMID 25775399, 2015).
melanoma (84 papers, 2006 to 2026). A malignant, usually aggressive tumor composed of atypical, neoplastic melanocytes. "In line with findings in other cancers, FAP-positive melanoma-associated fibroblasts have been characterized to play an immunosuppressive role, which supports the potential of an FAP-directed therapy in melanoma." (PMID 39895413, 2025). "This was first evidenced by its identification in the invadopodia of melanoma LOX cells, where FAPα, initially termed “seprase”, was associated with gelatinolytic activity, underscoring its role in matrix degradation during melanoma invasion." (PMID 40918451, 2025). "It has been revealed that overexpression of FAP is associated with increased tumor cell migration and invasion in gastric cancer, melanoma, and osteosarcoma." (PMID 37316886, 2023). "High FAP mRNA was found in 10% and 4% of tumors, respectively, and was associated with shorter median OS (melanoma cohort: 5.5 vs. 32.4 mos, p = 0.046; glioblastoma cohort: 10.4 vs. 14 mos, p = 0.024)." (PMID 35052475, 2022). "Multiplex fluorescence immunohistochemistry, using two different Fb-associated markers (FSP1 and FAP), along with the tumour marker, showed melanoma cells and Fbs interacting within the OMC." (PMID 32488012, 2020). "This study examines the clinical significance of cancer-associated fibroblast (Thy1, SMA, FAP) profiles in pretreatment tumor specimens to determine their association with immunotherapy outcome in melanoma." (PMID 31337426, 2019). "Fibroblast activation protein α (FAP) is a gelatinase implicated in tissue remodeling and tumor invasion expressed primarily in smooth muscle and also found in some melanoma cell lines." (PMID 19146682, 2009). "FAP, which is rarely expressed in healthy adult tissue, is involved in tissue remodeling processes and has been shown to be highly expressed on the surface of cancer-associated fibroblasts in the stroma of most human solid tumors, including melanoma." (PMID 39895413, 2025). "The ability of [68Ga]-Ga-FAPI to identify lesions that were inaccessible to imaging with [18F]-F-FDG due to activation in the tumor stroma confirms its potential as a diagnostic tool for melanoma and other tumors with high FAPα expression in the stroma, with possible therapeutic applications." (PMID 40918451, 2025). "To test this hypothesis, we used a replication-defective adenovirus (Ad)-based vaccine expressing FAP given together with an Ad vaccine expressing multiple epitopes from melanoma-associated antigens (MAAs) in two mouse melanoma models." (PMID 26943036, 2016). "An alternative spliced FAP-α was later identified in the human melanoma cell line LOX which encodes a truncated isoform which encodes a 239 amino acid polypeptide with a molecular weight of 27 kDa that precisely overlaps the carboxylterminal catalytic region of the wild type FAP-α." (PMID 24885257, 2014). "Similarly, in murine melanoma models, the vaccination-based depletion of FAP+ stromal cells has been linked to the reduction of immunosuppressive cell frequencies and functions, resulting in a robust CD8+ T cell response and prolonged survival of melanoma-bearing mice." (PMID 36338519, 2022). "For example, the FAP inhibitor talabostat/BXCL701 has been used in a phase II trial as a single agent for patients with metastatic colorectal cancer or in association with cisplatin in melanoma and is currently tested in association with anti-PD-1 therapy in advance solid cancers (NCT04171219)." (PMID 36338519, 2022). "The potential for targeting FAPα in melanoma stroma stems from the critical role of CAFs in establishing an aggressive tumor microenvironment." (PMID 40918451, 2025). "In a separate study, the diagnostic potential of [68Ga]-Ga-FAPI, a radioligand targeting FAPα, was investigated in patients with malignant melanoma." (PMID 40918451, 2025).
melanoma (continued). "In a C57BL/6 syngeneic mouse model with B16-F10 melanoma, FAPα and CD26 mRNAs were found to be co-expressed in the tumor, draining lymph nodes, and spleen, yet absent in B16-F10 cells cultivated in culture in vitro." (PMID 40918451, 2025). "Despite its low doses, PNT6555 demonstrates potential as a precise and safe therapy for tumors with high FAPα expression, including melanoma, though further refinement is necessary to enhance efficacy." (PMID 40918451, 2025). "More recent studies have demonstrated that melanoma cells can “reprogram” normal dermal fibroblasts into CAFs expressing high levels of FAPα." (PMID 40918451, 2025). "For instance, in advanced melanoma, α-SMA+ CD90+ FAP+ fibroblasts have been implicated in the therapeutic efficacy of anti-PD-1 Ab monotherapy." (PMID 41008624, 2025). "A fourth-generation CAR-T therapy targeting Nectin4/FAPα in solid tumors (excluding melanoma) is currently in clinical trials (NCT03932565)." (PMID 40918451, 2025). "A 55-year-old man with advanced end-stage melanoma reported a significant reduction in pain after one cycle of [177Lu]Lu-FAP-2286, after which he progressed." (PMID 41463267, 2025). "Here, we report results of a clinical phase Ib study investigating the combination of FAP-IL2v with the anti–PD1 monoclonal antibody pembrolizumab for the treatment of patients with mainly anti–PD-1–resistant malignant melanoma." (PMID 39895413, 2025). "Among the 20 patients with FAPα-positive tumors, including melanoma, 10 received at least one cycle of therapy." (PMID 40918451, 2025). "In melanocytes and primary melanoma cells, FAPα expression was stimulated by ultraviolet radiation, whereas in an ovarian cancer cell line, FAPα induction was dependent on collagen I exposure." (PMID 39364020, 2024). "MART1 serves as a marker for melanoma cells, while FAP serves as a marker for activated fibroblasts." (PMID 39206698, 2024). "In a murine model of FAP-expressing B16 melanoma tumors, FAP-IL2v treatment induced strong CD8+ T- and NK-cell expansion, consistent with its expected pharmacodynamic effects." (PMID 39140264, 2024). "In the context of cancer diseases, the FAP overexpression by CAFs is well established, but this is also true for mesenchymal stem cells, sarcoma and melanoma cells, M2 TAMs, and adipocytes within the MET." (PMID 39765634, 2024). "Growth and angiogenic factors: angiopoietin-2, endoglin, fibroblast activation protein (FAP), melanoma inhibitory activity, and vascular endothelial growth factor-A (VEGF-A) were significantly (p < 0.0001) elevated in EC patients." (PMID 39511039, 2024). "Now it has been confirmed that the overexpression of FAP in several cancers such as breast, gastric, melanoma, and fibrosarcoma, can increase cell migration, invasion, differentiation, and growth, as well as angiogenesis." (PMID 37316886, 2023). "In melanoma, FAP+ CAFs induced TIGIT and BTLA expression on cytotoxic T lymphocytes via increased arginase activity." (PMID 37166418, 2023). "While the majority of tumor cell lines exhibited low FAP expression, human melanoma, brain glioma, and low-grade glioma cell lines showed elevated expression." (PMID 37490719, 2023). "We thus sought to examine the prognostic utility of high FAP mRNA in two independent cohorts of melanoma (n = 64), and glioblastoma (n = 155) from The Cancer Atlas Database (TCGA)." (PMID 35052475, 2022). "The FAP-targeted radiotherapy reduced tumor growth in both models and melanoma, resulting in tumor regression." (PMID 36230500, 2022). "B16-FAP melanoma tumors of the FAP-IL2v-treated and vehicle-treated groups were clearly detected with [68Ga]Ga-DOTA-Siglec-9 PET/CT." (PMID 35874707, 2022). "We used histology and longitudinal PET/CT imaging using the VAP-1-targeted [68Ga]Ga-DOTA-Siglec-9 to monitor the effect of FAP-IL2v treatment in the B16-FAP melanoma model, which comprises B16 cells recombinantly over-expressing murine FAP." (PMID 35874707, 2022).
melanoma (continued). "Here, we tested a promising new therapy targeting fibroblast activation protein (FAP) with a therapeutic radionuclide 177Lu alone and with immunotherapy in mouse models of melanoma and lung cancer." (PMID 36230500, 2022). "In the subcutaneous B16-FAP melanoma model, we found that FAP-IL2v significantly increased the tumor uptake of VAP-1-targeted [68Ga]Ga-DOTA-Siglec-9 7 days after baseline imaging, as measured by in vivo PET and ex vivo autoradiography methods." (PMID 35874707, 2022). "In this study, we focused on longitudinal quantitative PET/CT imaging with VAP-1-targeting [68Ga]Ga-DOTA-Siglec-9 to assess the pharmacodynamic effect of the novel tumor-targeting FAP-IL2v immunocytokine in mice bearing B16-FAP melanoma tumors." (PMID 35874707, 2022). "Deletion of stromal cells via targeting FAP using a vaccine significantly lowered PD-1 levels in preclinical models of melanoma." (PMID 35479076, 2022). "In our mouse model of melanoma, while treatment with either immunotherapy or FAP-targeted radiotherapy increased the M2 macrophage population, combined therapy resulted in a near complete obliteration of this population." (PMID 36230500, 2022). "In the current study, the murine B16 melanoma cell line was transfected with FAP to make tumors more likely to elicit an immune response." (PMID 35874707, 2022). "While FDG-PET has been used traditionally, FAP-PET imaging is an exciting new agent being used for many types of tumors including melanoma with the advantage of excellent visualization of tumors that have not traditionally exhibited high FDG activity." (PMID 35626272, 2022). "Fibroblasts activated by TGFβ were characterized by a high α-SMA level, whereas fibroblasts cultured with melanoma CM and from indirect co-culture displayed a high FAP-α level." (PMID 35538545, 2022). "Using a whole tumour cell vaccine genetically modified to express FAP in a murine model of melanoma and lung cancer, resulted in reduced tumour growth and prolonged survival that was dependent on enhanced CD8+ TIL infiltration." (PMID 35479076, 2022). "[125I]I-MIP-1232 showed high accumulation in FAP-positive SK-Mel-187 melanoma cells and trivial in an NCI-H69 cell line with low FAP expression." (PMID 34681246, 2021). "The labeling with the β-emitting 177Lu of both exhibited specific accumulation in FAP-positive human melanoma xenografts, providing a delay in tumor growth in vivo." (PMID 34681246, 2021). "First, all cultured MAFs were shown to express the fibroblast marker FAP and to be void of melanoma markers such as melan A and gp100." (PMID 34944793, 2021). "MAFs and normal dermal fibroblasts (DFs) were isolated from surgically resected melanomas and identified as Melan-A-/gp100-/FAP+ cells." (PMID 32328671, 2021). "In summary, data presented here demonstrate that combining a traditional cancer vaccine with a vaccine that selectively targets FAP+ fibroblasts reduces tumor progression and even achieves cures in mouse melanoma models." (PMID 26943036, 2016). "CAFs that selectively express FAP have been found in almost all human carcinomas, including melanoma." (PMID 27590504, 2016). "Val-boroPro, also called Talabostat, was the first inhibitor of the proteolytic activity of FAP α used in phase II clinical trials successively performed in patients with metastatic colon cancer, non-small cell lung cancer, and melanoma." (PMID 26985769, 2016). "Melanoma tissues were collected from mice and tumor sections were stained with an antibody anti-fibroblast activation protein α (FAPα), a common marker of activated fibroblasts in tumors." (PMID 27590504, 2016). "Here, we report that pharmacologic inhibition of A2BR with PSB1115, which inhibits tumor growth, decreased the number of fibroblast activation protein (FAP)-expressing cells in tumors in a mouse model of melanoma." (PMID 27590504, 2016).